BRAF (B-Raf proto-oncogene, serine/threonine kinase)
Diseases named in the same sentence as BRAF in open-access papers (continued):
Sharing a sentence is not in itself a finding about the gene and the disease.
tumor (continued). "The identification of mechanisms underlying tumor development in BRAF wild-type LEAT cases represents a major challenge for future studies, which also requires a reliable terminology and histopathological classification of these tumor entities." (PMID 24858213, 2014). "High weight, hip, waist, WHR and BMI were associated with an increased risk of BRAF wild type tumours, but none of the anthropometric factors were associated with risk of BRAF-mutated CRC, neither in the overall nor in the sex-stratified analysis." (PMID 24918610, 2014). "Previous treatment strategies have been hampered by the heterogeneity of the disease – escape of residual cells from radiotherapy, emergence of resistance to BRAF inhibition, etc – and a strategy which could target the tumor as a whole has eluded researchers." (PMID 25566505, 2014). "The BRAF V600E mutation was observed in 63.6% (119/187) of tumor tissues, predominantly in PTC specimens, and no BRAF mutation was identified in other benign-type thyroid diseases." (PMID 24396464, 2014). "Likewise, a higher frequency of MSI especially of the MSI-High phenotype, which is a poor prognostic factor for CRC, has been reported to be more prevalent in right side compared with left side in the BRAF mutant tumours." (PMID 25361007, 2014). "In tumours that had no BRAF or NRAS mutation, low PTEN was significantly associated with poor overall survival [HR 95%CI)=0.27 (0.12, 0.64), P=0.003]." (PMID 24830350, 2014). "Inconsistencies of BRAF and KIT mutations between tumor biopsies and CTCs were described." (PMID 24743024, 2014). "So far, no increased risk of paradoxical tumor development has been observed, as has been described with BRAF inhibitors." (PMID 24713450, 2014). "Our data showed that BRAF and PIK3CA mutations were related to tumor site." (PMID 25367198, 2014). "In BRAF-mutant cell lines, the activation of Wnt/β-catenin signaling in combination with BRAFi synergistically enhanced apoptosis in vitro and increased inhibition of tumor growth in vivo." (PMID 24733413, 2014). "It is well established that BRAF mutations play a role in melanomagenesis; however, without additional genetic alterations, tumor development is restricted by OIS." (PMID 24743024, 2014). "Recent reports have also demonstrated that the therapeutic efficacy of targeted therapies, including c-Kit and BRAF inhibitors may depend on anti-tumor T-cell responses." (PMID 25594040, 2014). "Similarly, the inhibition of BRAF both directly inhibits tumor growth but also appears to activate the immune system." (PMID 25089198, 2014). "In this context, the success of this combination therapy suggests both inhibition of the BRAF fusion protein by sorafenib and of the downstream mTOR pathway by temsirolimus synergizes, although the specific mechanism of tumor regression awaits further investigation." (PMID 24422672, 2014). "However, we did not see any significant associations of EDMs with clinicopathological parameters, including sex, age, tumor location and tumor stage, CIMP, KRAS, and BRAF mutations." (PMID 25124163, 2014). "Although BRAF mutation (V600E) is reported in approximately only 25% of ATC, suggesting its involvement in tumor progression together with other genetic markers, it could be exploitable as potential therapeutic target." (PMID 25097549, 2014). "Further, the influence of BRAF-mutations and MMR-deficiency on tumor growth dynamics and plasticity may provide valuable insights into the biology of CRC." (PMID 24600585, 2014). "A murine adoptive cell therapy model was utilized to illustrate that selective BRAF inhibitor PLX4720 could increase tumor infiltration of adoptively transferred T cells and enhance the antitumor activity of the T cells." (PMID 25610709, 2014).
tumor (continued). "In contrast, an infiltrating tumor growth pattern is significantly more frequent in tumors with activating BRAF-mutations, while no impact of KRAS-mutations was observed." (PMID 24600585, 2014). "High waist- and hip measures were associated with an increased risk of KRAS wild type tumours (ptrend = 0.045 and ptrend = 0.043), KRAS-mutated tumours (ptrend = 0.007 and ptrend = <0.001), as well as BRAF wild type tumours (ptrend = <0.001 and ptrend = <0.001)." (PMID 24918610, 2014). "Associations between MEIS1 promoter methylation and BRAF mutation status, MSI and tumor location." (PMID 24244575, 2013). "However, reactivation of tumor progression after response to BRAF inhibitors can be achieved by tumor cells with an increased copy number of BRAFV600E." (PMID 23515890, 2013). "On the other hand, if a tumor exhibits high genetic instability driving widespread metastasis – e.g., BRAF mutant melanoma – then reducing tumor replication by damping down RAS-ERK signaling could slow worsening instability." (PMID 24377088, 2013). "The expression of BRAF mutation was not correlated with age, tumor location, diagnostic interval, tumor numbers or family cancer history." (PMID 24759670, 2013). "The activation of mTOR pathway by BRAF is consistent with our previous studies on human tumours." (PMID 23904987, 2013). "A likely explanation for this is that V600E-driven tumour cells also typically have higher levels of MKPs, which could to some extent compensate for the loss of ERK to BRAF feedback." (PMID 22812510, 2013). "Hence, Mφ depletion during BRAF-induced tumor initiation results in a profound remodelling of the tumor stroma, characterized by depletion of CAFs." (PMID 23372702, 2013). "Indeed, the use of a certified test to assess the BRAF status of tumour DNA costs at least twice as much as the use of in-house techniques." (PMID 24119386, 2013). "One study showed the absence of a BRAF mutation in 35 ESCCs, and the other showed that only 1 tumor harbored a BRAF mutation among 80 ESCC tumors." (PMID 23274581, 2013). "Univariate analysis, which considers individual variables contributing to MEIS1 promoter methylation (BRAF mutation status, MSI status, and tumor location), showed that BRAFp.V600E had the highest association with MEIS1 promoter methylation (OR = 13.0, CI = 5.2 - 33.0, P = 0.0001)." (PMID 24244575, 2013). "While the data currently presented should be interpreted carefully due to the limited number of patients studied, the association of low BRAF and NRAS expression with benefit from anti-tumor therapy as well as improved relapse-free and overall survival is interesting." (PMID 23673558, 2013). "PD0325901 treatment, dramatically inhibited growth of melanosphere-generated xenografts and determined impaired tumor vascularization of both mutated- and wild type-BRAF tumors, in the absence of mice toxicity." (PMID 24238212, 2013). "KRAS mutations were observed in only one sample and no tumor was found to harbor a BRAF V600E point mutation." (PMID 23637996, 2013). "We combined tumour mutation data from the Cancer Genome Atlas with matched patient genetic data, and tested for germline variants that associate with somatic mutation of the EGFR pathway (including EGFR, KRAS, BRAF, PTEN and PIK3CA)." (PMID 24152305, 2013).
tumor (continued). "The G469A mutation has been reported to have no enhancing effect on BRAF but it has been reported that kinase-dead BRAF mutations of D594 can have an indirect effect on tumor progression by enhancing CRAF activity." (PMID 23658559, 2013). "Similarly, among BRAF-wild type cases, 76.1% were seen in AREG-high and 50.7% in EREG-high tumours, while of BRAF-mutated cases only two out of six (33.3%) were observed in AREG-high and none in EREG-high tumours." (PMID 23374602, 2013). "MLH1 promoter methylation may be significantly associated with gender, tumor location, tumor differentiation, MSI, MLH1 protein expression, and BRAF mutation." (PMID 23555617, 2013). "In tumors harboring the V600E mutation, BRAF seems to be the key proliferation driver; thus, vemurafenib causes dramatic tumor shrinkage in patients with V600E-mutated tumors but not in tumors wild-type for BRAF." (PMID 23673558, 2013). "Although treatment with BRAF inhibitors, such as vemurafenib and dabrafenib, can result in the rapid onset of tumour response in many patients, intrinsic and/or acquired resistance means these are often temporary, with a median time to progression of less than 7 months." (PMID 22640478, 2012). "This possibility is further supported by recent data from a large retrospective study of BRAF and NRAS genotyping results demonstrating a small fraction of patients in which both BRAF and NRAS mutations were detected in their tumor specimen, possibly due to intratumor heterogeneity." (PMID 22235286, 2012). "Similarly, the results of the present study show that, although the BRAF genotype of the CTC was similar to that of the resected primary tumours, there were still some important mismatches." (PMID 22281663, 2012). "Patients with mCRC should have their tumor checked for BRAF mutation if they do not have KRAS mutation, to see if they are eligible for clinical trials for BRAF mutation inhibitors or drugs targeting the MAPK pathway." (PMID 22792460, 2012). "CDKN2A methylation positivity was associated with MSI (p = 0.025), BRAF mutation (p < 0.0001), higher tumor grade (p < 0.0001), mucinous histology (p = 0.0209) but not with KRAS mutation." (PMID 22925370, 2012). "E6201 is in a Phase I clinical trial for advanced solid malignancies that had an expansion phase to specifically include patients with BRAF mutant tumours (including brain metastases) (NCT00794781, ClinicalTrials.gov), and outcome analysis is currently maturing." (PMID 23039341, 2012). "This is accompanied by an early mutation of the BRAF oncogene, and acquisition of the CpG Island Methylator Phenotype (CIMP) which involves widespread promoter hypermethylation and subsequent silencing of key tumour suppressor genes." (PMID 23110075, 2012). "Gain-of-function mutations of RAS, BRAF, PIK3CA genes, or loss of tumor suppressor function of PTEN, resulting in continuous activation of the RAS-mitogen-activated protein kinase (MAPK) or phosphoinositide 3-kinase (PI3K) pathways, characterize most colorectal cancers (CRC)." (PMID 23136868, 2012). "Understanding the mutation status of RAS, BRAF and PI3K may also be informative for predicting tumor sensitivity resistance and would be important for future work." (PMID 23228035, 2012). "No patients with wildtype KRAS or BRAF tumor tissue genotypes had mutations in their respective cpDNA." (PMID 23144797, 2012). "Strangely, despite correlating BRAF mutational status to anti-tumour activity with E6201, phosphorylated ERK1/2 levels did not correlate with the magnitude of cell growth inhibition." (PMID 23039341, 2012). "This suggests that a large proportion of BRAF mutant cells in the resistant tumor did not harbor the NRAS mutation." (PMID 22235286, 2012). "ASLNAqPCR quantification of the mutated to wild type allele ratio clearly indicated the presence of tumor cell subclones in 7 of the 16 discrepant KRAS results (cases 1, 8, 9, 10, 11, 12) and in 3 of the 5 discrepant BRAF results (cases 2, 3)." (PMID 22558339, 2012).
tumor (continued). "We report here the development, validation, and clinical implementation of a multiplexed assay designed to simultaneously detect 43 recurrent mutations in BRAF, KIT, NRAS, GNA11, GNAQ, and CTNNB1 using tumor-derived DNA from formalin-fixed paraffin-embedded (FFPE) tissues." (PMID 22536370, 2012). "One strategy may be to use the two drugs sequentially; for example, to start with a BRAF inhibitor to reduce the tumour load, then use ipilimumab to maintain the response; or start with ipilimumab and provide vemurafenib afterwards to reduce the tumour burden." (PMID 22640478, 2012). "Mutations of PIK3CA, may coexist with either KRAS or BRAF within the same tumor, but KRAS and BRAF mutations appear to be mutually exclusive." (PMID 22586484, 2012). "One RCT study compared BRAF mutation in patients’ serum level with tumor samples but had no data on wild type BRAF status." (PMID 23056577, 2012). "We also tested expression of each protein against all other clinicopathological variables (age, gender, Dukes stage, post-operative chemotherapy, pre-operative radiotherapy, site of tumour, KRAS mutation status, BRAF mutation status, MSI and trial group, i.e. placebo/rofecoxib)." (PMID 23154512, 2012). "The presence of a mixture of BRAF mutated and non-mutated cells in the original tumor sample cannot be excluded." (PMID 23162534, 2012). "Furthermore, all the methylated MSI tumors had mutations in BRAF, whereas the methylated MSS tumor was wild type." (PMID 21909432, 2011). "However, little is known about the interrelationship between tumor-infiltrating T cells, MSI, and other molecular features of CRC, including CIMP, global DNA hypomethylation, or KRAS, BRAF and PIK3CA mutations." (PMID 24212797, 2011). "The patients with wt-BRAF tumours have higher response rates than the patients harbouring the BRAF V600E mutation, but the difference was not statistically significant." (PMID 22933967, 2011). "The absence of KRAS and BRAF mutations in our set of benign tumours is consistent with the paucity of somatic events observed in independent reports." (PMID 22163003, 2011). "However, at the time, very little is known about the interrelationship between TILs, MSI, and other tumour molecular features, such as the CpG island methylator phenotype (CIMP), global DNA hypomethylation, and KRAS, BRAF, and PIK3CA mutations." (PMID 22110523, 2011). "In the PETACC-3 study which included stage II and stage III cancers, BRAF tumor mutation was found in 7.9% of cases and there was no significant variability with tumor stage." (PMID 24212832, 2011). "Yet, the new forthcoming genetic features of primary tumours, for example, the BRAF or KIT mutation, are not taken into account up to now within the classifications but certainly merit reflection in the future." (PMID 22007305, 2011). "Cells of various kinds of benign, static neoplasms in vivo show markers of senescence, for example, in melanocytic nevi, which generally carry activating v-raf murine sarcoma viral oncogene homolog B1 (BRAF) or neuroblastoma RAS viral oncogene homolog (NRAS) mutations." (PMID 21418545, 2011). "While MSI in HNPCC tumours is caused by germline mutations in mismatch repair (MMR) genes, MSI in sporadic tumours is often associated with MLH1 promoter methylation and accompanied by somatic BRAF mutations." (PMID 21901162, 2011). "Mutations in BRAF and PTEN were associated: four adenocarcinomas had PTEN mutations, mostly in poly-A tracts, and all 4 CRC were MSI+ and proximally located, typical of defective DNA mismatch repair tumours." (PMID 21473780, 2011). "Collectively, these data demonstrate that interfering with signaling pathways which facilitate the invasion of drug-resistant tumor cells may represents a cytostatic therapy that could complement BRAF inhibitor therapeutics." (PMID 21917148, 2011).
tumor (continued). "In order to assess any relationship between oncogenic activation or loss of tumour suppressor function in the PI3K/AKT and MAPK/ERK signalling pathways, mutations in PIK3CA, PTEN, BRAF and K-RAS, as well as loss of PTEN expression, were tested in relation to each other." (PMID 21473780, 2011). "We identified 149 control patients with advanced cancers who tested negative for BRAF mutations in the same time period and who were matched on a 1∶2 basis by tumor type with mutBRAF patients." (PMID 22039425, 2011). "CIMP-high CRCs were found to be associated with older age, female sex, proximal tumor location, poorly differentiated or mucinous histology, and higher frequencies of MSI-high and BRAF mutation, and nearly all of these characteristics are similar to those of MSI-high carcinomas." (PMID 21827707, 2011). "Our data confirmed the notion that BRAF mutations are frequently found in sporadic MSI tumours, and support the previous observation of BRAF mutations in about 5% of CRCs without MSI." (PMID 21901162, 2011). "The primary tumour of this case (PM-17) was wild type for BRAF by conventional sequencing." (PMID 21224857, 2011). "Clinical trials with several TKIs targeting RET, and to a lesser extent BRAF, and other TKRs have shown positive results, with about one-third of DeTC showing a reduction in tumor size up to 50%, with the longest treatment duration of approximately three-four years." (PMID 20628483, 2010). "Our data reveal another paradigm of BRAF-mediated signaling that promotes tumor progression." (PMID 20141835, 2010). "A phase I trial of patients with metastatic melanoma, thyroid, rectal, or ovarian carcinoma receiving PLX4032 showed tumor regression in five of seven (83%) patients with V600E BRAF and two of four patients (50%) with unknown V600E status." (PMID 24281076, 2010). "Furthermore, the combination of MSI and BRAF mutation, as detected for the MSI tumor described, is most frequently found for CpG island methylation phenotype 1 (CIMP1) tumors which are associated with MLH1 promoter methylations." (PMID 21203531, 2010). "Patients with MSI-H and BRAF-mutated tumours experienced significantly lower PFS (3.1 vs 11.4 months; P=0.008) and OS (14.5 vs 35.5 months; P=0.004) in comparison with those with MSI-H and BRAF wt tumours." (PMID 20485284, 2010). "Theoretically this would cause BRAF-mediated CRAF activation, which may not only induce resistance, but could potentially promote tumor growth." (PMID 20141835, 2010). "The combination of an MSS tumour without a BRAF mutation and no methylation of the MLH1 gene was observed in 260 tumours, and 19 tumours had a combination of MSS with BRAF mutation and no MLH1 methylation." (PMID 20051945, 2010). "New evidence suggests that patients with KRAS, BRAF or PTEN mutations experience fewer clinical responses to these drugs, compared with patients with wild-type tumours; moreover, molecular analysis, particularly of KRAS, is routinely being performed in standard molecular pathology laboratories." (PMID 19935791, 2010). "CIMP+ CRC is associated with distinct clinicopathological and molecular features including proximal tumor location, preponderance in elderly females, poorly differentiated and mucinous tumor histology, microsatellite instability (MSI) and frequent BRAF V600E mutation." (PMID 20492682, 2010). "A total of 45 MSI-H tumours were classified as not being associated with LS because they had MLH1 methylation; 39 of these tumours also had BRAF mutation, whereas 6 had no BRAF mutation." (PMID 20051945, 2010).